NDFIP1 (Nedd4 family interacting protein 1)
Description:
Activates HECT domain-containing E3 ubiquitin-protein ligases, including NEDD4 and ITCH, and consequently modulates the stability of their targets. As a result, controls many cellular processes. Prevents chronic T-helper cell-mediated inflammation by activating ITCH and thus controlling JUNB degradation (By similarity). Promotes pancreatic beta cell death through degradation of JUNB and inhibition of the unfolded protein response, leading to reduction of insulin secretion. Restricts the production of pro-inflammatory cytokines in effector Th17 T-cells by promoting ITCH-mediated ubiquitination and degradation of RORC (By similarity). Together with NDFIP2, limits the cytokine signaling and expansion of effector Th2 T-cells by promoting degradation of JAK1, probably by ITCH- and NEDD4L-mediated ubiquitination (By similarity). Regulates peripheral T-cell tolerance to self and foreign antigens, forcing the exit of naive CD4+ T-cells from the cell cycle before they become effector T-cells (By similarity). Negatively regulates RLR-mediated antiviral response by promoting SMURF1-mediated ubiquitination and subsequent degradation of MAVS. Negatively regulates KCNH2 potassium channel activity by decreasing its cell-surface expression and interfering with channel maturation through recruitment of NEDD4L to the Golgi apparatus where it mediates KCNH2 degradation. In cortical neurons, mediates the ubiquitination of the divalent metal transporter SLC11A2/DMT1 by NEDD4L, leading to its down-regulation and protection of the cells from cobalt and iron toxicity. Important for normal development of dendrites and dendritic spines in cortex (By similarity). Enhances the ubiquitination of BRAT1 mediated by: NEDD4, NEDD4L and ITCH and is required for the nuclear localization of ubiquitinated BRAT1. Enhances the ITCH-mediated ubiquitination of MAP3K7 by recruiting E2 ubiquitin-conjugating enzyme UBE2L3 to ITCH (By similarity). Modulates EGFR signaling through multiple pathways. In particular, may regulate the ratio of AKT1-to-MAPK8 signaling in response to EGF, acting on AKT1 probably through PTEN destabilization and on MAPK8 through ITCH-dependent MAP2K4 inactivation. As a result, may control cell growth rate. Inhibits cell proliferation by promoting PTEN nuclear localization and changing its signaling specificity.
Synonyms: N4WBP5; MGC10924
Tractability: Antibody: UniProt places it where antibodies can reach, with high confidence; UniProt predicts a signal peptide or a membrane-spanning region; its Gene Ontology location is reachable by antibodies, with medium confidence. PROTAC: UniProt records ubiquitination sites on it; ubiquitination databases record sites on it.
Gene: Protein-coding gene on chromosome 5 (142,108,762 to 142,154,440, forward strand). Ensembl gene ENSG00000131507.
Subcellular location: Endosome membrane; Golgi apparatus membrane; Synapse, synaptosome; Cell projection, dendrite; Secreted
Gene Ontology:
Molecular function: protein binding
Biological process: intracellular iron ion homeostasis; positive regulation of canonical NF-kappaB signal transduction; positive regulation of protein ubiquitination; proteasome-mediated ubiquitin-dependent protein catabolic process; ubiquitin-dependent protein catabolic process; metal ion transport; vacuolar transport
Cellular component: endosome membrane; extracellular region; perinuclear region of cytoplasm; endoplasmic reticulum; Golgi apparatus; cytoplasm; dendrite; Golgi membrane; synapse
Genetic constraint (gnomAD): Loss-of-function variants: 6 observed, 20.34 expected, observed/expected ratio (o/e) 0.29, 90% interval 0.16 to 0.58. The upper end of that interval is the gene's LOEUF score, 0.58, which puts it in group 2 of 6, group 1 being the genes least tolerant of losing a copy. Missense variants: 160 observed, 212.73 expected, observed/expected ratio (o/e) 0.75, 90% interval 0.66 to 0.86. Synonymous variants: 80 observed, 81.12 expected, observed/expected ratio (o/e) 0.99, 90% interval 0.82 to 1.19.
Homologues: Orthologues: chimpanzee NDFIP1 (99% identical), dog NDFIP1 (98% identical), rat Ndfip1 (98% identical), mouse Ndfip1 (97% identical), pig NDFIP1 (92% identical), macaque NDFIP1 (91% identical), guinea pig NDFIP1 (91% identical), rabbit NDFIP1 (85% identical), tropical clawed frog ndfip1 (85% identical), zebrafish ndfip1l (80% identical), zebrafish ndfip1 (73% identical), Drosophila melanogaster Ndfip (32% identical). Paralogues in human: NDFIP2 (61% identical).
Diseases named in the same sentence as NDFIP1 in open-access papers:
NDFIP1 is named in the same sentence as 47 diseases in open-access papers, as found by Europe PMC text mining. Sharing a sentence is not in itself a finding about the gene and the disease. The quoted sentences say what the papers report.
asthma (10 papers, 2014 to 2025). "Therapeutics designed to mimic Ndfip1, and activate Itch, would be predicted to have high efficacy in treating asthma while having a minimal effect on anti-viral immune responses." (PMID 28051111, 2017). "Similar to previous studies, we also observed pleiotropy for a number of loci in particular PTPN22 for JRA, T1DM, and Thyroiditis, IL5 for Eosinophilia, Asthma, and EoE and NDFIP1 for Mental Retardation traits and Cerebral Palsy." (PMID 25477900, 2014). "For example, Ndfip1 encodes a regulatory protein that enhances activity of the ubiquitin ligase ITCH to negatively regulate inflammation and has been associated with asthma risk in GWAS studies." (PMID 38712036, 2025). "For example, Ndfip1 encodes a regulatory protein that enhances the activity of the ubiquitin ligase ITCH to negatively regulate inflammation and has been associated with asthma risk in GWAS studies." (PMID 40326866, 2025). "For example, whole blood QTLs related to genes known to affect asthma pathogenesis or severity (e.g. IL18R, ZFP57, BTN3A2, NDFIP1, SMAD3, CLEC16A, and TSLP) were associated with colocalization sites for asthma and neutrophil, eosinophil, monocyte and/or lymphocyte traits." (PMID 32600345, 2020).
colitis (4 papers, 2016 to 2025). Inflammation of the colon. "Similar to Itch−/− Th17 cells, when adoptively transferred, Ndfip1 deficient Th17cells produced more IL-17A and induced severe colitis, indicating a pivotal role for the NDFIP1-ITCH pathway in the regulation of IL-17A-mediated inflammation." (PMID 40821838, 2025). "Thus concurrent production of TNFα and IFNγ by Ndfip1-deficient Th17 cells, coupled with the observed destruction of the colon mucosa, may explain the severe weight loss seen in the colitis model." (PMID 28051111, 2017). "As we had previously observed, mice receiving either Ndfip1-deficient or -sufficient Treg cells did not develop colitis." (PMID 28580955, 2017). "In vivo, Th17 cells lacking Ndfip1 were more likely than their WT counterparts to maintain lineage commitment, based on production of IL-17A, were much more likely to co-produce other pathogenic cytokines, and caused more severe colitis." (PMID 28051111, 2017). "To test this we transferred naive WT, Ndfip2−/−, Ndfip1 cKO and cDKO CD4+ T cells into Rag1−/− recipients to induce colitis." (PMID 27088444, 2016). "When transferred in vivo, Th17 cells lacking Ndfip1 were more likely to maintain their ability to make IL-17, were more potent proinflammatory cytokine producers, and were powerful inducers of colitis." (PMID 28051111, 2017).
hepatocellular carcinoma (4 papers, 2022 to 2025). A malignant tumor that arises from hepatocytes. "As previously reported, NDFIP1 is regarded as a tumor suppressor in uveal melanoma, hepatocellular carcinoma, pancreatic ductal adenocarcinoma, and breast cancer." (PMID 36929005, 2023). "In one study, miR-873 activated the key glycolytic proteins AKT/mTOR via targeting NDFIP1 to promote hepatocellular carcinoma growth and metastasis." (PMID 36929005, 2023). "For instance, miR-873 inhibits the expression of NDFIP1 to promote the progression of hepatocellular carcinoma." (PMID 35264565, 2022). "Another study revealed that Ndfip1 is a direct target of miR-873, which depends on the NDFIP1/AKT/mTOR axis to exert inhibitory effects on hepatocellular carcinoma." (PMID 40129459, 2025).
breast carcinoma (3 papers, 2021 to 2023). "Using mass spectrometric analyses, we found that most elevated proteins in Ki8751-treated cancers were all mitochondrial proteins, namely NDFIP1, CLK1, and TEFM, suggesting that Ki8751 treatments may enhance mitochondrial biogenesis of breast cancer cells." (PMID 33628590, 2021).
neuroblastoma (3 papers, 2020 to 2025). Neuroblastoma (NB) is the most common solid, extracranial childhood tumor. "In the other study, genetic deletion of NDFIP1 resulted in a loss of PTEN nuclear compartmentalization and increased cell proliferation in a human neuroblastoma cell line SH-SY5Y." (PMID 36929005, 2023). "Therefore, in this study, we explored the neuroprotective effect of Ndfip1 against mitochondrial complex I inhibitor rotenone in a human dopaminergic neuroblastoma SH-SY5Y cell line and further elucidated its possible underlying mechanisms." (PMID 33469419, 2020). "Therefore, real-time quantitative PCR, western blotting and immunofluorescence were performed on human neuroblastoma SH-SY5Y cells to study the neuroprotective effects and possible mechanisms of Ndfip1 on rotenone-induced neurotoxicity and increase in α-syn protein levels." (PMID 33469419, 2020).
pancreatic ductal adenocarcinoma (3 papers, 2022 to 2024). An infiltrating adenocarcinoma that arises from the epithelial cells of the pancreas. "Some studies have previously reported that nicotine can promote the development of pancreatic ductal adenocarcinoma (PDAC) cells via the microRNA-155-5p/NEDD4 family-interacting protein 1 (NDFIP1) axis." (PMID 38785984, 2024). "In pancreatic ductal adenocarcinoma and HCC, NDFIP1 downregulation by miRNAs promotes tumor progression or epithelial-mesenchymal transition." (PMID 35264565, 2022).
allergic disease (2 papers, 2016 to 2020). An immune response that occurs following re-exposure to an innocuous antigen, and that requires the presence of existing antibodies against that antigen. "Our results are consistent with experimental studies investigating the role of Ndfip1 in autoimmune and allergic diseases." (PMID 27786273, 2016).
autoimmune disease (2 papers, 2014 to 2023). A disorder resulting from loss of function or tissue destruction of an organ or multiple organs, arising from humoral or cellular immune responses of the individual to their own tissue constituents. "As previously demonstrated, NDFIP1 participates in inflammatory, neurological, and autoimmune diseases, but recently, the downregulation of NDFIP1 promotes proliferation, invasion, epithelial mesenchymal transition (EMT), or glycolysis in several forms of cancer." (PMID 36929005, 2023). "Knocked-out mice and those carrying mutations or overexpressing ubiquitin ligases and deubiquitinases [such as autoimmune regulator (AIRE), Itch, Nedd4, Roquin, Cbl-b, TNFR-associated factor 6 (TRAF6), Act1, Peli1, NEDD4-family interacting protein 1 (Ndfip1), A20, CYLD] develop autoimmune diseases." (PMID 24917867, 2014).
Eosinophilia (2 papers, 2012 to 2014). "The high degree of esophageal inflammation, revealed by eosinophilia and epithelial hypertrophy, in Ndfip1-cKO animals bears a strong resemblance to the pathology of EoE and EGE." (PMID 22506022, 2012). "In this study, we found that treatment of Ndfip1-cKO mice with oral antibiotics did not significantly reduce T cell activation or gastrointestinal eosinophilia and inflammation." (PMID 22506022, 2012).
injury (2 papers, 2014 to 2020). Damage inflicted on the body as the direct or indirect result of an external force, with or without disruption of structural continuity. "In rodent injury models Ndfip1 has been identified as a neuroprotectant due to its upregulation in surviving neurons following stress caused through stroke or traumatic brain injury." (PMID 24475238, 2014). "It was reported that Ndfip1 is strongly expressed in surviving neurons around the site of injury following transient focal cerebral ischemia or traumatic brain injury to provide neuroprotection." (PMID 33469419, 2020). "Ndfip1 is an adaptor protein for the Nedd4 family of ubiquitin ligases and has been found to be upregulated in neurons after brain injury, including head trauma, stroke and metal toxicity." (PMID 24475238, 2014).
intrahepatic cholangiocarcinoma (2 papers, 2022 to 2024). A carcinoma that arises from the intrahepatic bile duct epithelium in any site of the intrahepatic biliary tree. "However, WWP1-mediated ubiquitination reduces NDFIP1 levels, promoting intrahepatic cholangiocarcinoma (ICC) cell proliferation and migration." (PMID 39949609, 2024).
anaphylaxis (1 paper, 2016). An acute hypersensitivity reaction that occurs from exposure to an allergen. "The loss of mast cell-Nedd4-2/Ndfip1 activity is significant biologically, as it results in exacerbated mediator release in vitro and sustained IgE-mediated anaphylaxis-associated inflammation in vivo." (PMID 27786273, 2016).
Autoimmunity (1 paper, 2010). The occurrence of an immune reaction against the organism's own cells or tissues. "AIP4-knockout mice and Ndfip1-knockout mice both develop severe autoimmunity, making a strong case for the importance of adaptors in enabling substrate-ligase interaction, at least in some scenarios." (PMID 20646264, 2010).
Cerebral atrophy (1 paper, 2014). Atrophy (wasting, decrease in size of cells or tissue) affecting the cerebrum. "In fact, cerebral atrophy is one of the main findings in Ndfip1 KO mice." (PMID 25477900, 2014).
Cerebral ischemia (1 paper, 2025). Restriction of arterial blood supply to the brain associated with insufficient oxygenation to support the metabolic requirements of the tissue. "Genetic deletion of Ndfip1 revealed that Ndfip1 promotes PTEN ubiquitination and its nuclear trafficking, to promote neuronal survival after cerebral ischemia." (PMID 39808388, 2025).
Cognitive impairment (1 paper, 2023). Abnormal cognition is characterized by deficits in thinking, reasoning, or remembering. "It is also worth to explore whether Ndfip1 may play a role in neurological disorders that are related to cognitive impairment, such as Rett syndrome." (PMID 37023120, 2023).
keloid (1 paper, 2024). An irregularly shaped, elevated mark on the skin caused by deposits of excessive amounts of collagen during wound healing. "More recent genetic research has identified several genes, such as SMAD3, EN2, and NDFIP1, that may play crucial roles in keloid pathogenesis." (PMID 39119435, 2024).
lymphopenia (1 paper, 2017). Reduction in the number of lymphocytes. "In summary, in a setting where Treg cells are pushed to undergo lymphopenia-induced proliferation, Ndfip1-deficient Treg cells have an advantage in growth and expansion, which leads to a large increase in total numbers of Ndfip1-deficient current and and former Treg cells." (PMID 28580955, 2017).
melanoma (1 paper, 2019). A malignant, usually aggressive tumor composed of atypical, neoplastic melanocytes. "ROH island analyses identified several annotated genes (SPRY4, NDFIP1, HSP90AB1 and IMPDH2), which may play a role for further studies on equine melanoma." (PMID 30836959, 2019). "By means of ROH island analyses, we identified the genes SPRY4, NDFIP1, IMPDH2, HSP90AB1, which might play an important role for further studies on equine melanoma." (PMID 30836959, 2019).
memory impairment (1 paper, 2023). "Our results are consistent with the notion that protein degradation, other than protein synthesis, also underlies the mechanism of memory formation, but the physiological mechanisms underlying Ndfip1-regulated memory impairment remains to be elucidated." (PMID 37023120, 2023). "Although we have shown that Beclin 1 and PTEN are both the endogenous ubiquitination targets of Nedd4 in the hippocampus, our results do not exclude the possibility that Beclin 1 and PTEN are also the ubiquitination targets of other Nedd family proteins involved in Ndfip1-mediated memory impairment." (PMID 37023120, 2023). "Although we have shown that spatial training decreased endogenous Beclin 1 and PTEN ubiquitination in the hippocampus, it is not known whether Beclin 1 and PTEN are downstream effectors of Ndfip1 in Ndfip1-mediated memory impairment." (PMID 37023120, 2023).
Parkinson disease (1 paper, 2014). A progressive degenerative disorder of the central nervous system characterized by loss of dopamine producing neurons in the substantia nigra and the presence of Lewy bodies in the substantia nigra and locus coeruleus. "We report that in human Parkinson's brains increased iron concentrations in the substantia nigra are associated with upregulated levels of Ndfip1 in dopaminergic neurons containing α-synuclein deposits." (PMID 24475238, 2014). "We suggest that in Parkinson's disease, increased iron levels are associated with increased Ndfip1 expression for the regulation of DMT1, including abnormal Ndfip1 activation in non-neuronal cell types such as astrocytes." (PMID 24475238, 2014).
Stroke (1 paper, 2014). Sudden impairment of blood flow to a part of the brain due to occlusion or rupture of an artery to the brain. "In rodents after traumatic brain injury or stroke, Ndfip1 upregulation is maximal in surviving neurons at the lesion periphery rather than the core where most cells are necrotic." (PMID 24475238, 2014). "However, this comparison needs to take into account that PD is a degenerative disease (unlike trauma and stroke which are acute events), therefore Ndfip1 upregulation here might also serve totally different functions." (PMID 24475238, 2014).